APOE (apolipoprotein E)
Diseases named in the same sentence as APOE in open-access papers (continued):
Sharing a sentence is not in itself a finding about the gene and the disease.
cognitive decline (continued). "None of the interactions was significant (p = 0.3, for PRS-Alz 4 × PGS-Int 7, p = 0.1, for PRS-Alz 5 × PGS-Int 7 and p = 0.9, for APOE × PGS-Int 7) suggesting that APOE, and the polygenic contributions to AD and intelligence do not influence each other’s effect on cognitive decline." (PMID 34615922, 2021). "Therefore, cognitive decline after stroke may not be accelerated by the presence of ApoE ε4, which is consistent with the Chicago Health and Aging Project (CHAP) study, suggesting that cognitive decline before and after stroke was not significantly different among those with the ApoE ε4 allele." (PMID 40349252, 2025).
Cognitive impairment (1,022 papers, 2007 to 2026). Abnormal cognition is characterized by deficits in thinking, reasoning, or remembering. "(2012) proposed a synergistic interaction between the COMT rs4680 G/G genotype and APOE‐ε4, increasing susceptibility to cognitive impairments." (PMID 41476008, 2026). "Overall, the mediation analysis suggests that for anxiety, hallucinations, delusions, and agitation the APOE locus signal is only partially mediated by the association of APOE ε4 with cognitive impairment." (PMID 39974048, 2025). "A similar association was observed in a small population study in China, which suggested that ApoE gene polymorphism is associated with cognitive impairment in post-stroke patients." (PMID 40349252, 2025). "Animal studies have demonstrated that homozygous ApoE-deficient mice have neurodegenerative changes, synaptic deficits, and cognitive impairments and that these abnormalities also are seen if ApoE is selectively knocked out only in the brain." (PMID 41123760, 2025). "In this cross-sectional study, underweight and carriage of the ApoE ε4 allele were independently associated with cognitive impairment." (PMID 41439935, 2025). "It is well-established that the Apolipoprotein E (APOE) genotype is strongly associated with cognitive impairment and CSVD markers." (PMID 40607185, 2025). "A recent study regards the genotype APOE ε2/ε4 as a risk factor for developing more severe AD-related pathology (especially Aβ), mild cognitive impairment (MCI), and late-onset AD." (PMID 40407905, 2025). "This study aimed to examine associations between APOE ε4, apathy, and antidepressant use with progression from cognitively normal (CN) to mild cognitive impairments (MCI), and MCI to ADD." (PMID 40227643, 2025). "The APOE gene, which is the risk factor in AD, is also a potential predictor to predict cognitive impairment in PD." (PMID 40153789, 2025). "Upon adjusting for age, sex, education years, and APOE ε4 genotype, the associations with cognitive impairment remained significant for HV+ and FDG (IP)+ (OR = 71.15 and 11.22, respectively)." (PMID 39989286, 2025). "Women who carry the APOE-ε4 allele, in particular, are at greatest risk, showing accelerated progression, greater biomarker burden, and more pronounced motor and cognitive deficits relative to male carriers." (PMID 41479611, 2025). "Their findings indicated a positive association with cognitive impairment, predominantly associated with Pb; additionally, the presence of the APOE ε4 genotype heightened the relationship between cognitive impairment and exposure to Pb and element mixture." (PMID 39940989, 2025). "Collectively, our data indicated that whereas human APOE can cause less Aβ pathology than mouse APOE, human APOE4 significantly aggravates the deposition of Aβ compared to human APOE3 in AD mice long before causing cognitive impairment." (PMID 40075551, 2025). "We observed a significant association between APOE-ε4 status and cognitive impairment in both European and African ancestries samples." (PMID 41264616, 2025). "APOE E4 dosage was associated with greater odds of reporting hallucinations and cognitive impairment in addition to carrier status." (PMID 40926580, 2025). "Consistent with this, we found that APOE ε4 was positively associated with apathy, but the effect was fully mediated by cognitive impairment severity." (PMID 39974048, 2025). "A marginal interaction between APOE ε4 genotype and recreation-related PA on cognitive impairment risk was identified (P-value = 4.48 × 10− 2)." (PMID 39789564, 2025). "MBI-psychosis linked to higher risk of cognitive impairment (HR = 3.6, p < 0.0001); APOE ε4 modifies risk (HR = 3.4, p = 0.02)." (PMID 40657582, 2025). "Both objective (e.g., actigraphy) and subjective sleep measures predicted cognitive impairment, while cerebrospinal fluid (CSF) biomarkers and apolipoprotein E epsilon 4 (APOE ε4) genotype moderated these associations." (PMID 40688896, 2025).
Cognitive impairment (continued). "An increasing number of studies have shown that cerebral blood flow is closely related to the course of AD and MCI, pathological markers, vascular pathological burden, the apolipoprotein E (ApoE) ε4 allele, and the conversion of cognitive impairment." (PMID 40529431, 2025). "First, this study was designed as a cross-sectional study and cannot prove a causal relationship between APOE and seizure frequency synergies and cognitive impairment in older people with epilepsy." (PMID 40405274, 2025). "Some studies have indicated that carriers of the ApoE ε4 are at an increased risk of developing cognitive impairment following a stroke." (PMID 40349252, 2025). "Previous studies have also found that brain-aging trajectories are associated with cognitive impairments, with factors such as apolipoprotein E (APOE) ε4 and amyloid β influencing these trajectories in the context of AD." (PMID 40177249, 2025). "Age at death, time between the last clinical visit/the last MRI and autopsy as well as years of education, percentage of carriers of the APOE ε4 allele, and overall levels of cognitive impairment and depression were similar in all groups." (PMID 39865328, 2025). "Apolipoproteins are responsible for transporting lipids between cells and are important for the maintenance of cognition, as knocking out ApoE results in cognitive deficits in an allele-dependent manner." (PMID 39596576, 2024). "Since the APOE gene polymorphism has been found to influence cognitive impairment in AD, it is considered a therapeutic target for the pathology." (PMID 39768823, 2024). "A significant reduction of miR-195 AD individuals carrying a single ApoE ε4 allele, while the overexpression rescued ApoE4-induced cognitive impairment and lysosomal deficits in iPSCs-derived brain cells of ApoE4+/+ AD individuals." (PMID 38790711, 2024). "The recent discovery of an association between the presence of an APOECh variant and delayed onset of cognitive impairment reinforces the potential of developing disease-modifying therapies for AD by targeting APOE." (PMID 39612244, 2024). "It has been suggested that the combination of ApoE-ε4 genotype and slow gait represents a greater risk factor for cognitive impairment." (PMID 39336934, 2024). "Recent studies have extended the scope of research to patients with cognitive impairment to understand the associations of ApoE with Aβ and how the degree of glycosylation affects the interaction." (PMID 39169951, 2024). "So far, many studies have explored the relationship between APOE polymorphisms and PD-related cognitive impairment." (PMID 38880878, 2024). "Sex differences in cognitive impairment, as well as in the association between APOE ε4 genotype and cognitive impairment, have also been observed in other conditions." (PMID 39886338, 2024). "Association between multiple lifestyle factors and cognitive impairment in participants with the APOE ε4 gene." (PMID 39639910, 2024). "Multiple logistic regressions were employed to estimate the association between childhood adversity and cognitive impairment, while controlling for covariates including education, gender, ethnicity, and APOE ε4 status." (PMID 39559893, 2024). "Conversely, males exhibited only cognitive deficits in short-term visuo-spatial memory (i.e., the Corsi Block-Tapping Task), and thus the overall impact of the APOE ε4 allele on cognitive performance appeared less pronounced in this group." (PMID 39886338, 2024). "In recent years, BDNF Val66Met polymorphism has been reported to interact with APOE ɛ4 on working memory, verbal and visual episodic memory, and the progression of mild cognitive impairment (MCI)." (PMID 38374884, 2024). "This dual approach allowed for a comprehensive understanding of cognitive outcomes and depression in temporal lobe epilepsy, revealing distinct patterns of cognitive deficits and depression associated with sex and APOE genotype." (PMID 39886338, 2024).
Cognitive impairment (continued). "The significant cognitive deficits we observed among females carrying the APOE ε4 allele highlight previously unexplored genetic and sex-related influences on cognition." (PMID 39886338, 2024). "Relationships between baseline plasma oxysterols, APOE status, serum lipids, and cognitive impairment risk were examined in 328 postmenopausal women from the Women's Health Initiative Memory Study." (PMID 38574442, 2024). "APOE haplotype and CSF Aβ biomarkers are associated with cognitive deficits in ALS and particularly with memory impairment." (PMID 38853763, 2024). "The complex interplay between IR and APOE has been implicated in the mechanisms of cognitive impairment." (PMID 38956564, 2024). "Findings indicated that loneliness moderated the relationship between APOE e4 allele status and cognitive impairment based on nurse and neuropsychology technician assessments." (PMID 38962235, 2024). "This supports the findings from the cut-off comparisons, where female carriers consistently demonstrated lower scores across various neuropsychological tests, confirming their heightened vulnerability to cognitive deficits linked to the APOE ε4 genotype." (PMID 39886338, 2024). "Our study also found that plasma APOE levels in patients with cognitive impairment were of diagnostic significance, and the ELISA detection method we used is more convenient and easier for patients and medical staff to accept." (PMID 38883967, 2024). "Here, we present the findings from a genome-wide association study on cognitive impairment in Russian long-living adults and the results of molecular modeling of the APOE protein." (PMID 37953886, 2023). "The idea that inflammatory mediators are linked to cognitive impairment is reinforced by experiments in apolipoprotein E (ApoE) knockout mice, which show induction of IL-6 and IL-8 in the brain microcirculation is associated with impaired cognition." (PMID 37174621, 2023). "For sporadic AD, the APOE 4 allele is the most important genetic risk factor, as well as for the earlier stages of cognitive decline represented by mild cognitive impairment (MCI), but its expression is poorly understood." (PMID 38132357, 2023). "In the present study, we aimed to explore the association of ApoE gene polymorphism with the cognitive functions, and the downstream mediator of specific ApoE allele(s) in leading to the cognitive impairment in Chinese Han T2DM patients." (PMID 37700547, 2023). "Within this model, both APOE*E4 status (HR, 2.08; 95% CI, 1.10-3.97) and years of education (HR, 1.14; 95% CI, 1.03-1.28) were significantly associated with a risk of cognitive impairment." (PMID 38048131, 2023). "Cognitive impairment following TBI is found to be associated with the level of apolipoprotein E ε4 (ApoE-ε4), which reduces brain metabolism in the medial temporal and prefrontal lobe of TBI patients." (PMID 37575301, 2023). "This contrasts with the relatively modest cross-sectional associations between APOE e4 and cognitive functioning at age 70 which suggests that the effect of APOE e4 on cognitive deficits becomes more manifest in later life." (PMID 36481934, 2023). "This research aimed to establish the correlation between COVID-19 and cognitive impairment, and the APOE gene polymorphism among outpatients." (PMID 38137059, 2023). "Apolipoprotein-E4 (ApoE4), the strongest genetic risk factor for sporadic Alzheimer’s disease, is also a risk factor for microvascular pathologies leading to cognitive impairment, particularly subcortical white matter injury." (PMID 37577565, 2023). "This research aimed to ascertain the link between Long-COVID-19-related cognitive impairment and APOE gene polymorphism in a larger sample of outpatients in a public university hospital IN Northeast Brazil." (PMID 38137059, 2023).
Cognitive impairment (continued). "We observed that APOE-ε4 genotype and lifetime incarceration were independently related with an increased risk for cognitive impairment among HRS participants (i.e., a “G+E model” of risk)." (PMID 38048316, 2023). "A preceding report found that the APOE genotype and CLOCK_T3111C variant seem to interact with cardiovascular risk factors in patients with cognitive impairment to influence the progression to AD." (PMID 36901420, 2023). "Previous studies report age, married status, male, diabetes, low income, low education, unfavourable cardiovascular health and carrying apolipoprotein E (APOE) e4 allele were risk factors of cognitive impairment." (PMID 36919826, 2023). "Our results agree with prior studies that have found an association of APOE-ε4 with increased β-amyloid pathology, tau neurotoxicity, and cognitive impairment." (PMID 38115150, 2023). "Apolipoprotein E (APOE) has been implicated in the acceleration of cognitive impairment in patients with Lewy body diseases." (PMID 37482615, 2023). "One study showed a positive association between PRS excluding APOE and P-tau181 levels only among participants with mild cognitive impairment." (PMID 37516890, 2023). "We then estimated the age-related trajectory of cognitive impairment as a function of APOE e4 genotype separately in PSEN1 E280A mutation carriers and non-carriers." (PMID 37612284, 2023). "The APOE ε4 allele also reduces the age of onset of AD-associated cognitive impairment by 7 to 9 years per copy." (PMID 36614219, 2023). "In both cohorts, compared to the Aβ PET negative group, the Aβ PET positive group was more likely to carry an APOE ε4 allele (p < 0.001) and was more likely to have cognitive impairment (p < 0.001)." (PMID 36998318, 2023). "Although the APOE ε4 allele is linked with an increased risk for depression and cognitive impairments, lifestyle factors such as physical activity and a resultant potential better motor condition appear to be associated with a better cognitive state." (PMID 38026513, 2023). "There were no intergroup differences in terms of age, years of education, and interval from PET imaging to blood collection; however, the Aβ+ group showed more severe cognitive impairment and included a higher proportion of women and APOE ε4 allele-carries." (PMID 37381042, 2023). "In this study, AD-pathology also mediated the association between APOE-ε4 and late-life cognitive impairment." (PMID 38115150, 2023). "We first estimated the age-related trajectory of cognitive impairment as a function of APOE e2 genotype separately in PSEN1 E280A mutation carriers and non-carriers." (PMID 37612284, 2023). "Logistic regression analyses of the association between ApoE polymorphisms and the risk of cognitive impairment." (PMID 37700547, 2023). "Here, we draw these two lines of research together to examine how incarceration history and APOE-ε4 genotype combine to produce risk for neurodegeneration as indicated by cognitive impairment." (PMID 38048316, 2023). "The genome-wide association study showed that the APOE gene plays a significant role in the development of cognitive impairment in long-living adults." (PMID 37953886, 2023). "As before, we found that association between Lifetime Incarceration and Cognitive Impairment were virtually unchanged when APOE-ε4 genotype was included in the model (Model 2.3)." (PMID 38048316, 2023). "Higher educational attainment was related to higher global cognition in PSEN1 carriers and mitigated the cognitive impairment associated with APOE e4." (PMID 37612284, 2023). "APOE ε4 polymorphism has been recently described as a possible association with cognitive deficits in COVID-19 patients." (PMID 38137059, 2023). "Our study found that APOE ε4 genotype (heterozygote) is modestly associated with cognitive impairment in IADL among individuals with PD." (PMID 38026513, 2023).